AREG (amphiregulin)
Diseases named in the same sentence as AREG in open-access papers (continued):
Sharing a sentence is not in itself a finding about the gene and the disease.
cancer (continued). "Other SASP factors that facilitate EMT in cancer cells include the pro-inflammatory factors IL-6 and IL-8, Serine protease inhibitor Kazal-type 1 (SPINK1), amphiregulin (AREG), epiregulin (ERPG), and WNT16B." (PMID 37046588, 2023). "AREG/EGFR-mediated Treg/CAF coupling controls bifurcation of CAF and is a critical barrier for cancer immunotherapy." (PMID 37611111, 2023). "The violin plot analysis revealed that most of the signature genes were predominantly expressed in cancer cells, with the exception of RTN1 and AREG, which exhibited higher expression in monocytes/macrophages." (PMID 37845218, 2023). "Amphiregulin (AREG) gene, which belongs to the epidermal growth factor (EGF) family, is overexpressed in many cancer tissues." (PMID 36843929, 2023). "Pleural cancer cells interacted with mesothelial cells by MIF/CD74-CD44 complex and AREG/EGFR-ERBB2." (PMID 37649596, 2023). "Of note, AREG, ATF3, DUSP1, and ZFP36 were all related to cancers or pathways in cancer, and numerous studies have reported a role for these genes in different tumors." (PMID 35372438, 2022). "To confirm cancer cells as the major source of HB-EGF and AREG release, we cocultured WT and Adam17–/– 4T1 and E0771 cells with BMDMs for 48 hours." (PMID 35998057, 2022). "i3 cancers showed higher expression of downstream MAPK components (DUSP4 and ETV5) and i2 cancers had overexpression of EGFR ligands, AREG and EREG." (PMID 35773407, 2022). "The results exhibited that the mRNA and protein expression levels of PLAU, APP, AREG and CAV2 were upregulated in cancer cells compared to normal cells." (PMID 36437265, 2022). "The role of AREG, STAG3, CAV1 and C19orf57 in cancer were analyzed through Gene set enrichment analysis (GSEA)." (PMID 33712015, 2021). "Among the identified DEGs, 5 candidate cancer-induced genes including BHLHE40, AREG, SOCS1, CCL5 and DDIT4 were selected for external validation on an independent set of PBMC samples of patients with various stages of HCC." (PMID 34045534, 2021). "Combining NPG with HO-1 inhibitor demonstrated down-regulation of genes involved in cancer cell invasion and proliferation (EGR1, CXCL2, AREG, CXCL3, EREG, CD3e, CD3g, CD74, and B2M) as compared to NPG or to control animals." (PMID 34066839, 2021). "AREG is a ligand of epidermal growth factor receptor (EGFR), which is aberrantly expressed and plays a vital role in numerous types of cancer by mediating the motility, metastasis, and proliferation of cancer cells." (PMID 34143198, 2021). "Subgroup-specific genes with strong effects on overall survival and high MIFs in the proposed weighted model involve the following cancer-related genes: ADH1C, BMP5, LCN2 and PLOD2 in GSE31210, CST1 in GSE37745, as well as AREG and COL4A3 in GSE29013." (PMID 34876106, 2021). "Subsequently, seven common genes, including FOSL1, S100A9, CXCL12, ID2, PRS6KA3, AREG, and DUSP6, have been used as the target biomarkers for cancer diagnosis and therapy." (PMID 34490085, 2021). "On this note, ADAM17 is associated with shedding of several EGFR family ligands (e.g., EGF, TGFα, and amphiregulin) in NSCLC and other cancers." (PMID 30833304, 2019). "As the target of both cetuximab and AG1478 is EGFR, a receptor physically recognized and interacted by AREG, it remains unclear whether pharmaceutically targeting AREG with a target‐specific antibody is more effective in minimizing the acquired resistance of cancer cells." (PMID 31493351, 2019). "In cancer cells carrying EGFR mutants such as T790M, AREG expression is markedly elevated, but mostly limited to lung malignancies." (PMID 31493351, 2019). "Top five up-regulated genes in malignant tumours were COL11A1, SFRP2, LCN2, COL2A1 and H19, while top up-regulated genes in benign tumours were MMP3, MMP1, AREG, PTHLH and SFRP2." (PMID 30517191, 2018). "Presence of AREG, p-EGFR, p-AKT and p-mTOR was confirmed in the cancer tissue, CRC cells and xenografts by immunohistochemistry (IHC)." (PMID 29419396, 2018).
cancer (continued). "EGF-like growth factor Amphiregulin (AREG), which is frequently upregulated in human cancers, reduces GSK3 activity and stabilizes Foxp3." (PMID 29102676, 2018). "AREG/EREG overexpression and activation of the EGF pathway is a feature of CIN-positive CRCs, especially for carcinomas of the distal colon." (PMID 30563495, 2018). "Although treatment arm and cancer stage were strong prognostic factors, IGF1R and AREG status were also independent prognostic factors." (PMID 26884344, 2017). "Removal of the tumor suppressor angiomotin (AMOT)/Merlin from the TJ position induces TEAD/AREG via the Hippo/YAP pathway and then enhances the migration, invasion and proliferation of cancer cells." (PMID 28071680, 2017). "It is known that removal of AMOT/Merlin from the TJ position induces TEAD/AREG via the Hippo/YAP pathway and then enhances the migration, invasion and proliferation of cancer cells." (PMID 28071680, 2017). "High levels of serum AREG have been shown to activate AKT and ERK signaling and promote early disease progression in cancer patients." (PMID 27713123, 2016). "In particular, angimotin/merlin removed from the TJ position induces TEAD/AREG via the YAP pathway and then enhances the cell migration, invasion and proliferation of cancer cells." (PMID 27036040, 2016). "Thus, AREG may be a particular important EGFR ligand in cancer biology." (PMID 27669890, 2016). "Amphiregulin (AREG), a well-characterized prognostic and metastatic biomarker of various types of cancers, has been extensively studied in malignancy and metastasis, validating our approach to identify genes putatively involved in metastasis." (PMID 26544896, 2015). "For example, the EGF-family ligands heparin-binding EGF-like growth factor, amphiregulin, and TGF-α are upregulated in cancer cells from many different cancer types, and TGF-α overexpression causes widespread epithelial hyperplasia in mice." (PMID 22242000, 2011). "In this respect, human cancer cells, which exhibit mesenchymal-like characteristics, express lower levels of EGF ligands, such as amphiregulin and epiregulin." (PMID 21750552, 2011). "Amphiregulin (AREG) is a member of the epidermal growth factor (EGF) family, which activates the EGF receptor (EGFR), influencing multiple tumorigenic characteristics of cancers." (PMID 39452130, 2024). "Additionally, miR193a-CM upregulated genes for S100A8, AKR1C1, AREG, and PLIN2 were shown to inhibit angiogenesis and cancer growth." (PMID 36766731, 2023). "Combined with findings from our current study, we speculate that AREG, ATF3, DUSP1, and ZFP36 may serve as a bridge between cancer and OSA." (PMID 35372438, 2022). "Macrophages educated with either HB-EGF– or AREG-knockdown cancer cells were not able to induce cancer cell invasion in either 4T1 or E0771 cells, indicating that in the cocultures amplified EGFR signaling is required." (PMID 35998057, 2022). "The expression levels of AREG and EREG ligands are coordinately regulated, and EGFR downstream signaling pathways can be activated by the autocrine/paracrine ligand loop to promote cancer progression." (PMID 34884633, 2021). "Amphiregulin (AREG), which is the ligand for epidermal growth factor receptor (EGFR), plays an important role in wound healing, as well as various aspects of tumorigenesis, metastasis, and angiogenesis in cancer tissue." (PMID 33500443, 2021). "GPR81 expression is significantly higher in cancer tissue compared to adjacent noncancerous tissues and GPR81 promotes cancer aggressiveness, malignant phenotype, cell migration, and promotes amphiregulin transcription, contributing to angiogenesis." (PMID 33718271, 2021). "We assumed that EGFR ligands, especially AREG and EREG, which are frequently co-expressed in carcinomas, might offer similar treatment opportunities." (PMID 33941851, 2021).
cancer (continued). "Through upregulation on downstream factors (amphiregulin, CTGF and CYR61), TAZ could induce many malignant phenotypes of cancer, e.g., cancer stem cell viability, EMT, increased migration and invasion abilities, and higher potential of metastasis." (PMID 33268765, 2020). "In line with our in vitro data, upregulated AREG was generally localized in the stroma, in sharp contrast to the adjacent cancer epithelium which had limited or no staining." (PMID 31493351, 2019). "Although AREG is expressed on monocytes and is well known for mediating apoptosis resistance in various cancer cell types, to our knowledge, there are no data focusing on the role of AREG in PICD of monocytes." (PMID 32082070, 2019). "Several studies found that activation of YAP enhances the downstream gene expression of EGFR ligands such as Amphiregulin (AREG) and Neuregulin 1 (NRG-1), and ERBB3 and ERBB4, to form an autocrine loop and reinforce the MAPK signaling pathway to induce cancer progression and drug resistance." (PMID 31387256, 2019). "Amphiregulin is a secreted EGFR ligand that regulates cellular growth and differentiation, immunity, inflammation, and tissue repair, and it is overexpressed in a variety of cancers." (PMID 31649887, 2019). "Furthermore, AREG affected downstream molecules like BIRC5, CCNA2, CCNB2, TOP2A, MMP9, MMP1, CXCR4, have roles in development and progression of various types of cancers." (PMID 30517191, 2018). "Additionally, the ridle is the only method that identified two genes AREG and TRPM4 from the ErbB signaling pathway and ion-channel family, respectively, which are known to be related to cancer." (PMID 28122498, 2017). "Furthermore, removal of the tumor suppressor AMOT/Merlin from the TJ position induces TEAD/AREG via the Hippo/YAP pathway and then enhances the migration, invasion and proliferation of cancer cells." (PMID 28071680, 2017). "We have shown that AREG and EREG are required for HGF-mediated migration and invasion in response to signaling from integrin α6β4, further demonstrating their importance to invasive properties of cancer cells." (PMID 28733611, 2017). "Several studies in these cancers have suggested that EGFR expression, EGFR gene copy number, or expression of other EGFR ligands (epiregulin and amphiregulin) might be potential biomarkers for efficacy of anti-EGFR antibodies." (PMID 29228748, 2017). "The tightly regulated EGF-induced AREG mRNA expression was partly lost in the OSCC cell lines and restoring its regulation may be a new target in cancer treatment." (PMID 27669890, 2016). "In contrast, this pathway might be redundant or irrelevant, perhaps due to a low level of activation by AREG and EREG, in cancer cells, thus rendering the blockade of EGFR by cetuximab ineffective." (PMID 27344184, 2016). "Since cancer extracellular matrix releases EGF and HBEGF, and AREG correlated to HBEGF expression, we hypothesized that extracellular EGF and/or HBEGF induced AREG overexpression in OSCC." (PMID 27669890, 2016). "Patients with high AREG expression had poor clinical response to cisplatin treatment, suggesting that AREG increased cisplatin resistance in the HNSCC, as revealed for several other carcinoma types." (PMID 27669890, 2016). "Women in the cancer-free cohort ranged in age from 18 to 78, and Amphiregulin levels were not correlated with age (R = 0.13)." (PMID 24010672, 2013). "The proportion of these women with circulating Amphiregulin above either the 90th or the 95th percentile of the normal range was not statistically significantly different from the cancer-free population." (PMID 24010672, 2013). "The importance of parallel interactions between fibroblasts and cancer cells was tested by simultaneously targeting fibroblast-secreted amphiregulin and the CCL7 receptor on cancer cells, and this was significantly more efficacious than blocking either pathway alone." (PMID 24068959, 2013).
cancer (continued). "We previously reported the distribution of serum Amphiregulin in 85 cancer-free women, and demonstrated that these levels do not vary with stage of the menstrual cycle." (PMID 24010672, 2013). "Indeed, a previous study has revealed a role of cancer cell-expressed ADAMTS1 in metastasis with a mechanism involving activation of epidermal growth factor receptor and ErbB-2 and shedding of amphiregulin and heparin-bound epidermal growth factor precursors." (PMID 22514714, 2012). "Amphiregulin has been thoroughly investigated for its role in a variety of cancers and other proliferative diseases, but not yet for its part in bacterial infections." (PMID 21298020, 2011). "Our results imply that SPHK1 may be the central controller of amplification loops of EGF, AREG and EREG-EGFR interactions that can contribute to cancer progression." (PMID 21936950, 2011). "AREG, ER, JAGL1, and LAMA5 are predominantly reported for proliferation induction in cancer cells." (PMID 20096135, 2010). "AREG and PDGF-A could be detected in not only fibroblasts but also in cancer and endothelial cells, however PN expressed exclusively in CCA fibroblasts." (PMID 20096135, 2010). "In addition, an antibody blocking PD-L1 significantly increased death of the respective cancer cells, but inclusion of the anti-AREG antibody did not significantly enhance cancer cell death in this assay." (PMID 40666944, 2025). "ADAM17 proteolytically cleaves and activates several EGFR ligands such as epiregulin, transforming growth factor alpha (TGF-alpha), amphiregulin (AREG) and heparin-binding EGF-like growth factor (HB-EGF) and may thus contribute to cancer progression through EGFR activation." (PMID 36140519, 2022). "Finally, to obtain further insights into potentially relevant mechanisms in OSA pathogenesis, we used GSEA to analyze the signaling pathways related to AREG, ATF3, ZFP36, and DUSP1, and found that all four markers were related to inflammation and cancer-related pathways." (PMID 35372438, 2022). "We found that both HB-EGF and AREG were secreted by the cancer cells but not by the macrophages." (PMID 35998057, 2022). "Cancer cells with low expression of AREG and EREG may possibly indicated that it not sensitive to anti-EGFR therapies." (PMID 34884633, 2021). "EGFR is overepressed in many cancer types and activated by a variate of ligands, including besides EGF also the transforming growth factor-alpha (TGFA), heparin-binding EGF-like growth factor (HBEGF), betacellulin (BTC), amphiregulin (AREG) and epiregulin (EREG) and epigen (EPGN)." (PMID 32119655, 2020). "Therefore, locally elevated estrogen formation affects the development and progression of cancer tissues and cells (HCC, HepG2) by activating the rapid signalling pathway mediated via amphiregulin (AREG; a member of the EGF family), a ligand of EGF-R (epidermal growth factor receptor)." (PMID 32290381, 2020). "Among ADAM17 substrates, IL‐6R, TNFα, Notch1, and EGFR family ligands (e.g., TGFα, amphiregulin, epiregulin, and neuregulin‐1) promote the proliferation, survival, migration, and/or invasion of tumor cells (Zunke & Rose‐John, 2017), thus suggesting a prominent role for ADAM17 in cancer." (PMID 30833304, 2019). "Melatonin significantly suppressed amphiregulin transcripts in MEL and MEPT mammary glands, suggesting that amphiregulin together with the higher PRA:PRB balance and other factors may contribute to reducing cancer development in MEPT mice." (PMID 31355130, 2019). "To substantiate AREG inducibility in vivo, we analyzed a subset of patients whose pre‐ and postchemotherapy biospecimens were both accessible, and found remarkably upregulated AREG in the stroma, but not cancer epithelium, of each individual after chemotherapy." (PMID 31493351, 2019).
cancer (continued). "Thus, our data suggest that AREG represents one of the major TME‐derived soluble factors and precisely reflects the development of an in vivo SASP, and thus can be exploited to assess the magnitude of the SASP in cancer patients after clinical therapy." (PMID 31493351, 2019). "In our work, the SASP potently drives therapeutic resistance by not only enhancing the survival of cancer cells against chemotherapeutic agents but also consolidating the immune checkpoint potential against CTL and NK cell activities, a process that is mainly mediated by a soluble factor AREG." (PMID 31493351, 2019). "Therefore, amphiregulin interaction with the receptor is less efficient than EGF or TGF alpha at negative feedback mechanisms such as downregulation and degradation of the receptor, so this is advantageous for cancer growth." (PMID 29682205, 2018). "This may reflect AREG induced increased cancer cell motility, migration and infiltrative growth, which may explain the poor prognosis as AREG did not inhibit cisplatin cytotoxicity." (PMID 27669890, 2016). "However, despite several reports showing a potential link between cisplatin resistance and increased AREG expression in various cancers, AREG expression levels did not correlate to cisplatin resistance in the current 11 OSCC cell lines." (PMID 27669890, 2016). "Finally, AREG and HBEGF expression levels were positively correlated in the carcinomas." (PMID 27669890, 2016). "In addition to the mutational status of KRAS, the epidermal growth factor receptor (EGFR) ligands amphiregulin (AREG) and epiregulin (EREG) might function as bona fide biomarkers of cetuximab (Ctx) sensitivity for most EGFR-driven carcinomas." (PMID 22491422, 2012). "Moreover, the result from our group about the expressions of ADAM12, AREG, ER, JAGL1, PDGF-A, PN and SCG2 in whole CCA tissues (n = 20) showed that only AREG, PDGF-A and PN had higher level in cancer than those in benign liver tissues with statistical significance (data not shown)." (PMID 20096135, 2010). "In addition, specific targeting of EGFR ligands (e.g. amphiregulin, heparin-binding EGF-like growth factor) by neutralizing antibodies or small molecules represents a promising therapeutic approach, as it inhibits the proliferation and metastatic events in breast and hepatocellular carcinoma cells." (PMID 37853459, 2023). "Thus, in addition to the profound gene expression pattern change, AREG induced a striking epithelial‐to‐endothelial transition (hereby termed EET), suggesting a salient capacity of AREG in reprogramming the transcriptomics of cancer cells in the context of treatment‐remodeled TME." (PMID 31493351, 2019). "Differential expression analysis between ER+ and ER– cancers identified over-expression of TTF1, LAF-4 and C-MYB (p ≤ 0.05), and between pCR vs non-pCRs, over-expression of CXCL9, AREG, B-MYB and under-expression of ABCG2." (PMID 28697743, 2017). "SOCS6 levels are low in several cancers, where they show a negative correlation with the levels of the YAP target Amphiregulin." (PMID 25180228, 2014). "We found that AREG, E1CAM, and GPRC5D had prognostic efficacy in the Human Protein Atlas (HPA), while their mRNA expression was not significantly different between cancer and normal tissues in the TCGA-HNSC database." (PMID 37106442, 2023).